MIR4665 (microRNA 4665)
Synonyms: hsa-mir-4665; mir-4665
Gene: MicroRNA gene on chromosome 9 (6,007,826 to 6,007,904, forward strand). Ensembl gene ENSG00000263575.
Homologues: Orthologues: chimpanzee MIR4665 (100% identical).